LAMB2P1 (laminin subunit beta 2 pseudogene 1)
Synonyms: formerly LAMB2L
Gene: Unprocessed pseudogene on chromosome 3 (49,140,086 to 49,160,851, reverse strand). Ensembl gene ENSG00000270441.
Diseases named in the same sentence as LAMB2P1 in open-access papers:
LAMB2P1 is named in the same sentence as 1 disease in open-access papers, as found by Europe PMC text mining. Sharing a sentence is not in itself a finding about the gene and the disease.
LAMB2P1 shares sentences with these, for which no sentence is quoted: ulnar-mammary syndrome (1 paper).